CCND1 (cyclin D1)
Diseases named in the same sentence as CCND1 in open-access papers (continued):
Sharing a sentence is not in itself a finding about the gene and the disease.
lung carcinoma (continued). "It has been reported that GS decreases the expression of gene products involved in proliferation (cyclin D1 and c-myc) by inhibition of NF-κB and IκBα kinase activation in human cells derived from lung carcinoma and leukaemia." (PMID 21364590, 2011). "Dysregulation of cyclin D1 was frequently found in theearly stage of tumorigenesis in many different cancers, and has been reported athigh levels in chromate induced lung cancers." (PMID 21437242, 2011). "The aim of this study is to evaluate the expression of cyclin D1 in lung cancer tissues by means of immunohistochemistry, and to analyze the relationship between the amount of tumor staining for cyclin D1 and overall survival." (PMID 20704822, 2010). "In vitro expression of RASSF1A in H1299 lung carcinoma cells inhibited cell cycle progression by negatively regulating the accumulation of cyclin D1 through a posttranscriptional mechanism." (PMID 20042089, 2009). "As examples of genetic polymorphisms that affect onset age of cancers other than that examined in this study, some reports discuss MMP-1 and DDB2 in lung cancer, and CCND1 in HNSCC and colorectal cancer." (PMID 17919326, 2007). "Similarly, IL-7 enhances bladder cancer invasion through NF-κB-mediated MMP-9 expression and promotes lung cancer proliferation by upregulating cyclin D1 via the c-FOS/c-Jun pathway." (PMID 41596598, 2026). "Moreover, Hsp90 inhibition promotes the degradation of the cell-cycle protein Cyclin D1, thereby blocking lung cancer cells from progressing from G1 to S phase and halting tumor cell division." (PMID 40869279, 2025). "Due to the more prevalent overexpression of cyclin D1 compared to other D-type cyclins in human cancers, development of selective IKKα inhibitors, also selective cyclin D1 inhibitors, may be beneficial for patients with specific types of lung cancer." (PMID 40763800, 2025). "In addition, Sorafenib had an effective antiproliferative impact by reducing cyclin-D1 expression, leading to cell cycle arrest in combination with other drugs in lung cancer." (PMID 40205002, 2025). "Linc00467 can target miR-4779 and miR-7978 in lung cancer to promote lung cancer cell proliferation, invasion and metastasis, and it can also adsorb miR-20b-5p to relieve the inhibitory effect of miR-20b-5p on CCND1 to promote lung adenocarcinoma cell growth." (PMID 39655078, 2024). "The results may provide evidence in support of the potential utilization of CCND1 rs9344 as a predictive biomarker for prognosis and chemotherapy sensitivity in Chinese patients with lung cancer in certain conditions." (PMID 38589850, 2024). "In addition, another study that explored curcumin-induced FOXO1 inhibition of lung cancer progression and metastasis found that activation of FOXO1 inhibited the spread of lung cancer cells by downregulating CCND1 gene expression." (PMID 36670858, 2023). "Likewise, tetracenomycinsare, an antibiotic produced by the Streptomyces and Nocardia species, induced cell cycle arrest in the lung cancer cells by decreasing the expression levels of cyclin D1 and CDK4 (cyclin-dependent kinase 4)." (PMID 38067602, 2023). "In another study it was reported that entacapone or tolcapone in combination with EGCG can reduce expression of cyclin D1 and consequently, resulting to G1 arrest induction in H1299 cells, whereas in CL‐13 lung cancer cells they found significant G2/M arrest, which was in parallel to our findings." (PMID 36534072, 2023). "In the present study, inhibition of PNO1‐induced p21 and suppressed CCND1 in lung cancer cells." (PMID 36625087, 2023).
lung carcinoma (continued). "Additionally, we examined these cellulosic derivatives with cytotoxic effects on lung cancer cells (A549) and colon cancer cells (Caco2), and we then examined the levels of β-Catenin, c-Myc, Cyclin D1, and MMP7 gene expression in A549 cells." (PMID 37666882, 2023). "The cyclin D1 overexpression was related to worse survival in patients with head and neck cancers, but not in patients with gastrointestinal (GI) tract, breast, bladder, or lung cancers." (PMID 37894399, 2023). "It was suggested that CCND1 may control the activity of lung cancer cells through mediating the PI3K/AKT pathway, but further validation was needed." (PMID 35246017, 2022). "In addition, CCND1-OE elevated tumor weight in mice and supported the tumorigenicity of lung cancer cells in vivo after 16 days." (PMID 35246017, 2022). "In this study, we studied the biological role and the molecular mechanisms of CCND1 in lung cancer." (PMID 35246017, 2022). "Thus, we revealed that CCND1, mediated by the nuclear translocation of NF-κB, promoted the progression of lung cancer through triggering PI3K/AKT signaling pathway." (PMID 35246017, 2022). "Our data revealed that NF-κB/CCND1/PI3K/AKT axis could act as a prospective diagnostic biomarker and a therapeutic option for lung cancer." (PMID 35246017, 2022). "We speculated that the differential expression of CCND1 may be the reason why the BP in lung cancer is mainly regulated by the cell cycle." (PMID 35246017, 2022). "Furthermore, they also conducted transwell experiments and the result indicated that let-7a inhibits migration and invasion of lung cancer cells by influencing cyclin D1." (PMID 36303933, 2022). "Our results propose that inhibition of CCND1 might be an attractive therapeutic target for lung cancer." (PMID 35246017, 2022). "Later, rescue experiments using SN50 and the PI3K/AKT signaling inhibitor PI3K-IN-1 revealed that suppression of NF-κB or impairment of the PI3K/AKT signaling could effectively counteract the oncogenic role of CCND1 in lung cancer in vitro and in vivo." (PMID 35246017, 2022). "In addition, LUT reduces the expression of cyclin D1 and cyclin D3, thereby inducing cycle arrest of lung cancer cells in the G1 phase (NCI-H1975 and NCI-H1650 cells)." (PMID 36172186, 2022). "In vivo, overexpression of CCND1 promoted lung cancer growth and metastasis." (PMID 35246017, 2022). "Beta-Caryophyllene exerting anti-proliferative activities in lung cancer cells A549 and NCI-H358 cells has been attributed to the induction of G 1 phase cell cycle arrest through downregulating cyclin D1, and other cyclin-dependent kinases, which was associated with upregulating p21CIP1 and p27KIP1." (PMID 36500446, 2022). "The tumor supporting role of CCND1 has been substantiated in lung cancer via a binding relation with microRNAs or long noncoding RNAs, indicating that the expression of CCND1 might be regulated by a myriad of mechanisms." (PMID 35246017, 2022). "In addition to DNA helicases, we also observed decreased Cyclin D1 protein, a cell cycle regulator, in MTHFD2 deficient lung cancer cells." (PMID 35790743, 2022). "The effect of CCND1 expression on the proliferation of lung cancer cells was firstly analyzed, and EdU staining of proliferating cells was followed by observation of the proportion of positive cells under fluorescence microscope to assess the cellular DNA replication." (PMID 35246017, 2022). "As well as detecting the same CCND1 CNV that was identified in lung cancer samples using a CNV-specific targeted assay, use of the Unified Assay revealed LOH in multiple chromosomes, thus providing a much more complete picture of the changes within these tumor samples." (PMID 36675685, 2022). "Through a series of experiments and analysis, we believe that CCND1 may be a key gene in the regulation of lung cancer, and has certain prognostic significance." (PMID 35246017, 2022).
lung carcinoma (continued). "Overincrease in cyclin D1 expression has been reported in many cancers including lung cancer." (PMID 36364001, 2022). "Importantly, CCND1 overexpression enhanced lung cancer cell proliferation, invasion and migration, and arrested the cell cycle at the S phase." (PMID 35246017, 2022). "Nevertheless, the mechanism by which CCND1 supports lung cancer development is yet to be expounded." (PMID 35246017, 2022). "Moreover, FXR, a transcription factor, has been suggested to be recruited to the CCND1 promoter and elevated its transcription in lung cancer." (PMID 35246017, 2022). "MiR-20b-5p could sponge with the 3′ untranslated region (3′ UTR) of CCND1, repressing the CCND1 expression in a lung cancer cell." (PMID 34068010, 2021). "Moreover, we showed that apatinib inhibited proliferation and induced apoptotic and autophagic death in lung cancer tumors, as evidenced by the decreased expression of Cyclin D1, Nrf2 and p62, but the increased expression of Cleaved Caspase 3 and LC3-II." (PMID 34429133, 2021). "Moreover, by promoting the expression of multiple target genes, including DDIAS, cyclin D1, IL-2, and IL-4, NFATc1 protects lung cancer cells against anticancer drug-induced death." (PMID 33859351, 2021). "Therefore, our findings revealed that licorice inhibit the expression of CDK4-Cyclin D1 complex would be critically important for prevention and treatment of lung cancers." (PMID 34641869, 2021). "TOB1 could inhibit the proliferation and metastasis of lung cancer cells through a series of downstream regulators, including cyclin D1, AKT signal transduction, BCL-2, BCL-XL, and SMAD4." (PMID 34604392, 2021). "Furthermore, like LCAT3 knockdown, FUBP1 knockdown also suppressed the migration of A549 and Calu1 lung cancer cells, and triggered G1 arrest by significantly reducing the levels of cyclin A2 and cyclin D1." (PMID 34274028, 2021). "In conclusion, our results demonstrated that AsA effectively inhibited the cell growth of lung cancer cells and that AsA could induce G1/S arrest and modulate the activity of Akt/Cyclin D1 pathway in lung cancer cells through an ROS-dependent mechanism." (PMID 32992455, 2020). "Notably, our results demonstrated that further inhibition of Cyclin K with siRNA in lung cancer cells led to insignificant effects on these phenotypes when Cyclin D1 was simultaneously knocked down." (PMID 33042275, 2020). "Key findings: CCND1 was co-overexpressed with FGFR1 in lung cancer patients." (PMID 32380883, 2020). "As was previously shown by proteomic analysis of lung carcinoma cells, the knockdown of YTHDF1 led to activation of cell cycle inhibitor p27Kip1 and suppression of cell cycle activator genes encoding CDK2, CDK4 and cyclin D1." (PMID 33317545, 2020). "Since a synthetic lethal interaction has been reported between KRAS mutants and CDK4, we asked whether expression of cyclin D1 and CDK4 might be associated with the KRAS mutation in lung cancer patients." (PMID 32104498, 2020). "Furthermore, bioinformatics analysis with TCGA database demonstrated that Cyclin K expression is positively correlated with both β-catenin and Cyclin D1 levels in lung cancer tissues." (PMID 33042275, 2020). "In addition, cyclin D1 overexpression has been proved to be related to poor prognosis in patients with cancers like lung cancer and oropharyngeal cancer." (PMID 32697404, 2020). "In the transcriptome of our EVs, we found also MIR490 that seems to have the role of tumor suppressor in lung cancer cells A549 and ovarian cancer by blocking the transcription of CCND1 and CDK1 respectively, two important genes involved in cell cycle progression." (PMID 32582296, 2020). "Compared with that in normal tissues, the expression of CCND1 is obviously higher in bladder cancer tissues, reproductive system tumours, gastric cancer tissues and lung cancer tissues, and it is correlated with the pathological type and clinical stage of the tumour." (PMID 32660514, 2020).
lung carcinoma (continued). "Notably, our efforts focused on an in vivo orthotropic mouse model, which closely mimics the clinical features of human lung cancer and clarifies that CCND1 plays a pivotal role in the initiation and metastasis of lung cancer." (PMID 32380883, 2020). "We demonstrated the co-expression of FGFR1 and CCND1 in lung cancer." (PMID 32380883, 2020). "Similarly, circ-CMPK1 was significantly downregulated in nonsmall cell lung cancer and promoted tumor growth by increasing the expression of cyclin D1 via sponging and inhibiting miR-302 activity." (PMID 32867570, 2020). "Besides cell cycle regulation, cyclin D1 contributes to DNA repair in human cervical carcinoma, lung cancer, prostate cancer, and esophageal cancer cells." (PMID 31591311, 2019). "Many studies have shown that cyclin D1 plays an important role in lung cancer progression." (PMID 31262974, 2019). "We first reported that Cx43 transfection of highly malignant murine lung carcinoma cells dramatically reduced their growth in vitro and tumorigenicity and was associated with increased expression of the cyclin-CDK inhibitor p27 and decreased cyclin D1." (PMID 30717421, 2019). "Cyclin D1 proteasomal degradation-mediated cell cycle arrest at the G0/G1 phase may be the important antitumour mechanism of tetracenomycin X in lung cancer cells." (PMID 30669360, 2019). "Moreover, stellettin B leads to cell cycle G1 phase arrest through the inhibition of cyclin D1 protein expression and induces autophagic flux in A549 lung cancer cells." (PMID 30769863, 2019). "In A549 and H1299 lung cancer cells, Zbed3 overexpression promoted cancer cell proliferation and invasiveness, as well as Wnt signalling and expression of downstream mediators, including β‐catenin, cyclin D1 and MMP7 (P < 0.05)." (PMID 30417576, 2019). "Expression of the major component in the Wnt pathway (glycogen synthase kinase-3β [GSK3β]) and downstream effectors of the Wnt pathway (β-catenin, Cyclin D1, c-Myc, and Survivin) was assessed by western blot in lung cancer cells in which HOXA4 had been overexpressed or knocked down." (PMID 29700285, 2018). "Our analysis also showed that SUVmax cannot predict expression of cyclin D1 in lung cancer." (PMID 29983647, 2018). "A study of the mechanisms indicated that BOS-102 could significantly block cell proliferation in human A549 lung cancer cells and effectively induce G0/G1 cell cycle arrest via targeting cyclin D1 and cyclin-dependent kinase 4 (CDK4)." (PMID 29370087, 2018). "Similarly, knockdown of claudin-2 by siRNA in lung cancer cells A549 was recently reported to decrease proliferation concomitant with decreases in cyclin-D1 and E1 expression, cell cycle progression factors." (PMID 29152115, 2017). "Mitochondrial dysfunction and oxidative stress of repeated exposure to urethane associated with over stimulation of IFN-γ-producing cells, CD11b + Gr-1 + phenotype, overexpression of NF-кB, COX-2, STAT3, IL-6 and cyclin D1 resulted in chronic inflammation and lung cancer." (PMID 28240047, 2017). "Rather than through these canonical signaling pathways that regulate c-Jun, we established here that c-Jun is directly phosphorylated and activated by TOPK in EGFR-TKI-refractory lung cancer cells, leading to the transcriptional activation of AP-1 target genes such as CCND1 and CDC2." (PMID 26745678, 2016). "In the present study, we observed that ART, DHA, and ARTS inhibited the expression level of Wnt5-a/b, down-regulated those of LRP6 and Dvl2, and subsequently reduced those of downstream genes mediated by β-catenin (i.e., nanog, sox2, oct3/4, and cyclin D1) in two lung cancer cell lines." (PMID 27119499, 2016).
lung carcinoma (continued). "Moreover, we evaluated the correlation between CCND1 mRNA and miR-326 expression in 39 lung cancer tissues." (PMID 26840018, 2016). "The growth-inhibitory role of miR-134 may be attributed to the fact thatmiR-134 targets 3′-UTR of CCND1 mRNA, and inhibits the expression of CCND1 in lung cancer cells." (PMID 27166267, 2016). "MiR-326 could regulate cell proliferation and migration of lung cancer by targeting phox2a, CCND1 and NSBP." (PMID 27835574, 2016). "In addition, miR-326 also inhibited cyclin D1, cyclin D2 and promoted p57 and p21 expression levels in lung cancer cells, which further contributed to the growth-delay efficacy of miR-326." (PMID 26840018, 2016). "In addition, miR-134 also inhibited cyclin D1, cyclin D2 and promoted p57 and p21 expression levels in lung cancer cells, which further contributed to the growth-delay efficacy of miR-134." (PMID 27166267, 2016). "The growth-inhibition role of miR-326 may attribute to that miR-326 targets 3′-UTR of CCND1 mRNA, and inhibits the expression of CCND1 in lung cancer cells." (PMID 26840018, 2016). "Moreover, we also revealed up-regulation of miR-326 suppresses lung cancer cell proliferation, migration, invasion and colony formation, and promotes lung cancer cell apoptosis, through targeting cyclin D1." (PMID 26840018, 2016). "Our experimental data may provide a strategy for targeting the miR-326/cyclin D1 interaction in a novel therapeutic application to treat lung cancer patients." (PMID 26840018, 2016). "In addition, inhibition of CCND1 expression promoted apoptosis in lung cancer cell (both A549 and SPC-A-1 cells)." (PMID 26840018, 2016). "In addition, inhibition of CCND1 expression promoted apoptosis in lung cancer cell (4.5-fold of increase or 3.4-fold of increase in caspase 3 activity, 2.1-fold of increase or 2.3-fold of increase in caspase 7 activity inA549 or SPC-A-1 cells)." (PMID 27166267, 2016). "We next examined the potential tumorigenicity of CCND1 in lung cancer." (PMID 26840018, 2016). "Taken together, our results suggested that the phosphoinositol 3-kinase (PI3K)-Akt-p21-cyclin D1 signaling pathway might contribute to the CUEDC2-induced G0/G1-to-S phase cell cycle arrest in lung cancer cells." (PMID 26023733, 2015). "In this study, we found that resibufogenin induced G1-phase arrest with the conversion of RB protein to the unphosphorylated form with down-regulation of cyclin D1 protein through the proteasomal degradation in human colon cancer HT-29 cells and human lung cancer A549 cells." (PMID 26121043, 2015). "Consistent with the decrease in phospho-CREB (p-CREB) levels, CCND1 mRNA levels also decreased in response to UA treatment in a concentration-dependent manner in lung cancer cells, suggesting that UA blocks the VRK1 downstream signaling pathway, as well as its enzymatic activity." (PMID 26412148, 2015). "Additionally, the expression of cyclin D1 was significantly up-regulated and similar results were reported for human lung cancer." (PMID 26427040, 2015). "Similar results for CYCLIN D1 were also obtained in lung cancer H358 cells (Fig6B)." (PMID 25143352, 2014). "Cyclin D1 is frequently overexpressed in a large number of cancers, including colorectal, gastric cancer, nonsmall cell lung cancer, and glioma by diverse mechanisms such as genomic amplification, chromosomal translocations, disruption of normal intercellular trafficking, and proteolysis." (PMID 24995320, 2014). "This raises the question whether ATDC mediated up-regulation of cyclin D1 and c-Myc in lung cancer cells results from an activation of wnt signal transduction pathway in which cyclin D1 and c-Myc are crucial components." (PMID 23776433, 2013). "Briefly, ATDC could promote lung cancer proliferation through NF-κB induced up-regulation of cyclin D1 and c-Myc." (PMID 23776433, 2013). "Cyclin B1 and cyclin D1 are usually over-expressed in lung cancer cells." (PMID 23739680, 2013).